MIR186 (microRNA 186)
Synonyms: hsa-mir-186; MIRN186; miR-186
Gene: MicroRNA gene on chromosome 1 (71,067,631 to 71,067,716, reverse strand). Ensembl gene ENSG00000207721.
Gene Ontology:
Biological process: miRNA-mediated post-transcriptional gene silencing
Cellular component: RISC complex
Homologues: Orthologues: chimpanzee ptr-mir-186 (100% identical), macaque mml-mir-186 (99% identical), rat Mir186 (95% identical), pig ssc-mir-186 (92% identical), guinea pig MIR186 (81% identical), mouse Mir186 (79% identical), rabbit MIR186 (70% identical).
Diseases named in the same sentence as MIR186 in open-access papers:
MIR186 is named in the same sentence as 4 diseases in open-access papers, as found by Europe PMC text mining. Sharing a sentence is not in itself a finding about the gene and the disease. The quoted sentences say what the papers report.
lung adenocarcinoma (1 paper, 2024). A carcinoma that arises from the lung and is characterized by the presence of malignant glandular epithelial cells. "The low expression levels of down-regulated DEGs PLA2G3, PCP4L1, NINJ2, MIR186, and KLRG1 were also statistically correlated with a shorter OS in lung adenocarcinoma." (PMID 38183079, 2024).
lung carcinoma (1 paper, 2024). "Another study demonstrated that MIR186 could inhibit lung cancer progression through targeting SIRT6." (PMID 38183079, 2024).
periodontal disease (1 paper, 2019). "PTGER3 (rs74086974; p-value 3.18 × 10− 6) is a candidate gene for the outcome of periodontal disease therapy, and MIR186 (rs74086974) is differentially expressed between gingiva in health versus periodontitis." (PMID 31533690, 2019).
MIR186 also shares sentences with these, for which no sentence is quoted: periodontitis (1 paper).